PPARG (peroxisome proliferator activated receptor gamma)
Diseases named in the same sentence as PPARG in open-access papers (continued):
Sharing a sentence is not in itself a finding about the gene and the disease.
asthma (continued). "Activation of PPARγ by synthetic agonists reduced the levels of Th2 cytokines and inhibited AHR, the influx of eosinophils and structural changes in the airway wall in murine OVA-challenge models of asthma." (PMID 33362766, 2020). "All five PPARG crystal complexes are classified as PPARG agonists, suggesting all 108 docked DCT-compounds promote the reduction of pro-inflammatory Th2 cytokines, eosinophils and macrophages, along with lessening asthma chronicity (PDB; Uniprot)." (PMID 32185106, 2020). "Nevertheless, the potential mechanism of how curcumin regulates NF-κB activation through PPARγ in the airway epithelium in asthma is still not very clear." (PMID 31073274, 2019). "While PPARG has been associated with airway inflammation, ETV4 has not yet been implicated in asthma, thus indicating the possibility of novel, disease-relevant discovery by NeTFactor." (PMID 31506535, 2019). "In light of these modest changes, the authors suggested that PPARγ agonist monotherapy is unlikely to represent a clinically useful intervention, at least in the context of relatively mild asthma." (PMID 22966222, 2012). "Furthermore, studies have demonstrated that PPARγ activation enhances the expression of glucocorticoid-induced leucine zipper (GILZ), an anti-inflammatory protein, thereby amplifying its role in suppressing inflammatory responses in asthma." (PMID 41149648, 2025). "Indeed, circulating iNKT cells from allergic asthma patients expressed significantly higher levels of ACC1, FASN, and PPARG than iNKT cells from healthy controls and nonallergic asthma patients." (PMID 37917548, 2023). "Furthermore, circulating iNKT cells from allergic-asthma patients expressed higher ACC1 and PPARG levels than the corresponding cells from non-allergic-asthma patients and healthy individuals." (PMID 37917548, 2023). "CLA in breast milk has been documented to modulate a variety of key processes in the pathogenesis of asthma, including PPARγ-dependent and non-dependent inflammation, arachidonoid production, and humoral immune responses, making it possible to be an effective therapy for infant asthma." (PMID 37958184, 2023). "Hence, PPARγ targeting might be exploited in cancer immunotherapy and in other ILC2-driven mediated disorders, such as asthma and allergy." (PMID 33953160, 2021). "However, whether PPARγ could influence on IgE production and whether PGE2 could regulate PPARγ in asthma was totally unclear." (PMID 32636842, 2020). "Because miR-98 is a known regulator of PPARγ, a transcription factor that plays a key role in mediating airway remodeling in prenatal nicotine exposure, we focused on examining the potential role of miR-98 in regulating NGF in airway remodeling and asthma therapy." (PMID 33082140, 2020). "Although PPARγ agonists are extremely promising to asthma therapy, unfortunately severe asthmatic patients treated with pioglitazone did not present with an improvement in asthma features and showed significant side effects." (PMID 33362766, 2020). "Furthermore, therapy with PPARγ agonist (pioglitazone and rosiglitazone) showed modest or no improvement in subjects with asthma, thereby implying insufficient intervention." (PMID 33574813, 2020). "These combined findings suggest that PPARγ expression is increased in response to acute or chronic inflammation in multiple cell types including ASM, and that PPARγ could be targeted to limit inflammation, airway remodeling, and increased ASM contraction in asthma." (PMID 22966222, 2012). "These diverse PPARγ-dependent and PPARγ-independent actions define numerous mechanisms whereby PPARγ ligands could regulate the altered proliferative, secretory and contractile functions of ASM contributing to asthma." (PMID 22966222, 2012).
asthma (continued). "Our recent study has shown that administration of PPARγ agonists, rosiglitazone and pioglitazone decreases the IL-17 protein and mRNA expression in the lung and reduces Th2 cytokine expression, AHR, and eosinophil activation, which are increased by induction of asthma." (PMID 20565710, 2010). "It has been reported that corticosteroids did not prevent TGFβ-induced collagen I production by ASM cells from individuals with or without asthma, and this suggests that PPARγ agonists may have a therapeutic advantage over corticosteroids in the regulation of lung fibrosis." (PMID 18000530, 2007). "These combined findings support further investigation of the potential for PPARγ agonists to target the noncontractile and contractile functions of ASM to improve outcomes for patients with poorly controlled asthma." (PMID 22966222, 2012). "Thus, we sorted the iNKT, Treg, CD4 +T, and CD8+ T cells from the peripheral blood mononuclear cells (PBMCs)of 10 healthy volunteers, 10 patients with allergic asthma, and 10 patients with nonallergic asthma and examined their mRNA expression of ACC1 and PPARG." (PMID 37917548, 2023). "Thus, iNKT cells from allergic asthma patients express higher ACC1, FASN and PPARG levels and lower levels of a glycolysis, which is accompanied with higher levels of IL4 and IL13 than iNKT cells from healthy controls and nonallergic asthma patients." (PMID 37917548, 2023).
thyroid cancer (87 papers, 2004 to 2026). "Previously, PPARG structural variants have been reported in thyroid cancer stemming from environmental radiation exposure." (PMID 39113632, 2024). "To validate diverse expression levels of PPARγ target genes and their potential diagnostic value in thyroid cancer, we next generated a unified, cancer type-specific, merged microarray dataset (MMD-THCA), as previously carried out for other major cancer types." (PMID 34680260, 2021). "Thyroid carcinomas harboring the CDS mutations in the LBD of PPARG were further found in COSMIC GRCh37 v94 database." (PMID 34680260, 2021). "The paired box 8 (PAX8)–peroxisome proliferator-activated receptor-γ (PPARγ) fusion gene (PAX8/PPARγ) is another prominent recombinant oncogene in thyroid cancer, occurring in up to 60% of FTC and follicular variant PTC (FVPTC)." (PMID 26886957, 2016). "More recently, PPARγ protein expression has been linked with the aggressiveness of thyroid cancer cells." (PMID 22934105, 2012). "Dysregulation of NTRK1, BRAF, Ras, and PAX/PPARγ has also been associated with the development and progression of other thyroid cancers." (PMID 22630170, 2012). "Many studies have examined use of other molecular markers including RAS, RET/PTC rearrangement, and/or PAX8/PPARγ rearrangement to improve the diagnostic accuracy of thyroid carcinomas." (PMID 23049733, 2012). "As a fatty acid transporter, FABP3 hypomethylation and consequently overexpression could enhance intracellular lipid flux and activate PPARγ/RXRα signaling, which is implicated in tumor proliferation of thyroid cancer." (PMID 41019337, 2025). "In addition, inactivation of PTEN and PPARG increased thyroid cancer aggressiveness and was associated with increased NF-kB activation." (PMID 31835496, 2019). "The recent findingsfrom a transgenic mouse study may provide an explanationfor why thyroid cancer is susceptible to treatment with PPARγ agonists." (PMID 18615184, 2008). "Furthermore, a fusionprotein derived from the paired box gene 8 (PAX8) and PPARγ genes (PPARγ-PAX-8) was detected in thyroid cancers,which causes PPARγ not only to be functionally inactivebut also to function as a dominantnegative form of PPARγ." (PMID 18528522, 2008). "Here, we observed that PPARγ target genes were expressed at significantly higher levels compared with benign tissues, suggesting that the PPARγ activation might increase the risk of developing thyroid cancer." (PMID 34680260, 2021). "BRAF mutation, RAS mutation, RET/PTC rearrangement, PAX8/PPARγ rearrangement, and TERT promoter mutation, are among the major molecular indicators linked to thyroid cancer." (PMID 38501105, 2024). "Most thyroid cancers contain one of several known driver mutations, such as the V600E substitution in BRAF, RAS mutation, RET gene fusion, or PAX8/PPARγ gene fusion." (PMID 38791384, 2024). "Extensive studies have shown that the activation of PPARγ by its ligands (either synthetic or endogenous) can inhibit the growth of thyroid cancer." (PMID 34557159, 2021). "Some studies have indicated that the expression of PPARγ is reduced in thyroid cancer while others revealed the normal expression of PPARγ or the inactivation of PPARγ by the Pax-8-PPAR-γ fusion protein (PPFP)." (PMID 34557159, 2021). "Chromosomal rearrangements of RET/PTC, and PAX8/PPARγ (peroxisome proliferator-activated receptor gamma) and point mutations in BRAF and RAS genes are the most common in thyroid cancer." (PMID 33996538, 2021). "Through targeted next-generation sequencing of thyroid cancer-related genes in monozygotic twins with papillary thyroid cancer (PTC), we identified common variants of the gene encoding peroxisome proliferator activated receptor gamma (PPARG)." (PMID 34680260, 2021).
thyroid cancer (continued). "PPARγ has been proposed as a therapeutic target in thyroid cancer, but although attempts have been made to correlate PPARγ expression with miR-27a, as yet there is no firm evidence linking miRNAs and PPARs in this type of cancer." (PMID 34638914, 2021). "FTC is a less common subtype of WDTC with 10–15% cases of all the thyroid carcinomas, driven by RAS, BRAFV600E mutations, and PAX8/PPARγ (Paired Box Gene 8/Peroxisome Proliferator-Activated Receptor Gamma) rearrangements." (PMID 35008887, 2021). "Since different cell lines, including breast, prostate, colon, bladder, and thyroid cancer cells express high levels of PPARγ, the potential role of PPARγ agonists in modulating cancer progression has been widely investigated." (PMID 32937951, 2020). "In TC, among those over-expressed in males, we found PPARG, previously reported in thyroid carcinomas, ERCC5, MYH11, LEMD2, ZNF133, and IDH1, the latter found to be mutated in thyroid carcinomas." (PMID 32849808, 2020). "While a meaningful conclusion about the efficacy of pioglitazone cannot be drawn from a single case study, the positive result does support follow-up investigations of the PPARγ agonist in this subset of thyroid cancer patients." (PMID 31614690, 2019). "PPARγ has a specific role in thyroid cancer because follicular thyroid cancer is the only known neoplasm to be associated with a PPARγ fusion gene product." (PMID 25866814, 2015). "Although gene expression data in human PPFP thyroid carcinomas are very limited, there is excellent overlap between the human data and our data, including the induction of PPARG target genes." (PMID 26595524, 2015). "The majority of thyroid carcinomas contain one of a small number of driver mutations, such as BRAF or RAS mutations, gene fusions involving RET, or gene fusions between PAX8 and PPARG." (PMID 26595524, 2015). "A recent report suggests an oncogenic function for PPARγ in human thyroid carcinoma with G9a as a negative regulator of its oncogenic activity." (PMID 25765655, 2015). "This is consistent with the fact that several PPARG target genes have been shown to be induced in human PPFP thyroid carcinomas." (PMID 26595524, 2015). "We recently reported that peroxisome proliferator-activated receptor gamma (PPARγ) confers an aggressive phenotype in thyroid cancer cells." (PMID 24645981, 2014). "Alterations of PPARG have been discovered in a large number of thyroid cancer samples, such as PAX8/PPARG fusion oncogene in follicular thyroid carcinoma and PTCs, and another PPARG agonist (RS54444) in ATCs." (PMID 24718460, 2014). "There have been several genetic abnormalities associated with thyroid carcinoma including point mutations such as those in the RAS and BRAF genes, and chromosomal rearrangements such as RET/PTC and PAX8/PPARγ." (PMID 23717622, 2013). "Conversely, when PPARγ was overexpressed in more differentiated thyroid cancer cells, there was increased growth and invasiveness in vitro." (PMID 22934105, 2012). "In conclusion, our in vitro and in vivo studies show that PPARγ contributes to more aggressive thyroid cancer properties including faster growth rate and increased invasiveness." (PMID 22194735, 2011). "Regarding specific mutations that constituted the panel for thyroid cancer diagnostic, RAS, BRAF, RET/PTC, and PAX8/PPARγ mutations had all a 100% positive predictive value for cancer." (PMID 22654559, 2011). "In one of the studies, 64% of undifferentiated thyroid cancers had a moderate or high expression of PPARγ whereas only 31% of DTC exhibited any PPARγ expression, lending an important tissue correlation with our cell line data." (PMID 22194735, 2011). "Two previous reports using thyroid cancer cells showed that the cell cycle inhibitors p21 and p27 were increased by agonist activation or overexpression of PPARγ." (PMID 22194735, 2011).
thyroid cancer (continued). "To determine if PPARγ plays a role in the invasive capacity of thyroid cancer cells, we depleted ATC cells of PPARγ and compared this with its overexpression in DTC cells." (PMID 22194735, 2011). "When PPARγ was overexpressed in more differentiated thyroid cancer BCPAP cells which lack PPARγ, there was increased growth and raised pRb and cyclin A and B1 levels." (PMID 22194735, 2011). "At least two previous studies utilized an shRNA strategy to knock down PPARγ in thyroid cancer cells." (PMID 22194735, 2011). "Although in vitrodata is promising, early studies using PPARγ agonists to treat iodine-insensitiverecurrent thyroid cancer are promising, but inconclusive so far." (PMID 18989374, 2008). "In thyroid cancer, theTRβPV/PV mouse model was usedto further elucidate the mechanism ofPPARγ tumorigenesis.TRβPV/PV mice were crossedwith PPARγ+/− mice to obtain TRβPV/PVPPARγ+/− offspring." (PMID 18989374, 2008). "PPARγ represents an attractivetherapeutic target in a variety of thyroid cancers, including anaplastic, follicular,and papillary thyroid cancers." (PMID 18989374, 2008). "PPARγ-mediatedpathways, however, are downregulated in these mice, hinting at a role for PPARγ inhibition in this thyroid cancer model." (PMID 18989374, 2008). "Normal, benign, and malignantthyroid tissues express PPARγ, with dysregulated expression in thyroid cancers." (PMID 19125177, 2008). "The objectives of the present work were: to study and compare the relative expression of PPARγ in normal, benign and malignant thyroid tissues and to correlate PPARγ immunostaining with clinical/pathological features of patients with thyroid cancer." (PMID 15238980, 2004). "PPARγ agonists and PPARγ overexpression led to a drastic reduction of the cell growth rate in PPARγ-expressing thyroid carcinoma cells." (PMID 15266333, 2004). "The PAX8/PPARγ rearrangement is a molecular abnormality found in thyroid carcinoma, especially FTC." (PMID 38501105, 2024). "Crosstalk between PPARG and ER suppresses the proliferation and migration of thyroid cancer cells." (PMID 36114448, 2022). "In detail, PPARγ agonists, HDAC inhibitors, PI3K/AKT inhibitors and MEK/ERK inhibitors, have been recommended for NIS over-expression and have caused improved iodine uptake in thyroid cancers." (PMID 33922518, 2021). "The cross-talk between ER and PPARγ can provide a new therapeutic strategy against thyroid cancer." (PMID 33996538, 2021). "Presented data suggested that PPARγ may promote growth and invasion of cancer cells and play a detrimental role in thyroid cancer." (PMID 34906147, 2021). "Despite the well-established role of the PAX8-PPARγ fusion oncogene, the expression landscape of experimentally validated PPARγ target genes remains unclear in thyroid carcinoma." (PMID 34680260, 2021). "Current diagnostic biomarkers in thyroid cancer include point mutations in the BRAF, NRAS, KRAS, HRAS genes, and rearrangements in paired box 8 (PAX8)/peroxisome proliferator-activated receptor gamma (PPARG) and RET." (PMID 33158279, 2020). "Peroxisome proliferator-activated receptor gamma (PPARγ) is a master regulator of adipocyte differentiation and is expressed in various types of cancers, such as breast, colon, prostate, thyroid cancers, and giant cell tumor of bone." (PMID 27401457, 2016). "We previously reported that PPARγ confers an aggressive phenotype in thyroid cancer cells." (PMID 24645981, 2014). "PPARγ levels are elevated in cells derived from undifferentiated (anaplastic) thyroid cancer." (PMID 22934105, 2012). "The expansion of knowledge regarding genetic mutations in thyroid cancers has led to the use of molecular markers as an indicator of prognosis and for the malignancy diagnosis especially in indeterminate FNA samples (BRAF, RAS, RET/PTC, and PAX8/PPARγ)." (PMID 23326756, 2012). "Therapies directed at PPARγ expression or a downstream target may lead to novel approaches to treat advanced thyroid cancer." (PMID 22194735, 2011).